IGSF23 (immunoglobulin superfamily member 23)
Description:
May be involved in osteoclast differentiation.
Tractability: Antibody: UniProt places it where antibodies can reach, with high confidence; its Gene Ontology location is reachable by antibodies, with high confidence; UniProt predicts a signal peptide or a membrane-spanning region.
Gene: Protein-coding gene on chromosome 19 (44,613,563 to 44,636,787, forward strand). Ensembl gene ENSG00000216588.
Subcellular location: Cell membrane
Subcellular location (Human Protein Atlas): Nucleoplasm; Cell Junctions
Gene Ontology:
Biological process: osteoclast differentiation; heterophilic cell-cell adhesion; homophilic cell-cell adhesion
Cellular component: plasma membrane
Genetic constraint (gnomAD): Loss-of-function variants: 12 observed, 15.9 expected, observed/expected ratio (o/e) 0.75, 90% interval 0.48 to 1.22. The upper end of that interval is the gene's LOEUF score, 1.22, which puts it in group 5 of 6, group 1 being the genes least tolerant of losing a copy. Missense variants: 213 observed, 246.68 expected, observed/expected ratio (o/e) 0.86, 90% interval 0.77 to 0.97. Synonymous variants: 85 observed, 95.24 expected, observed/expected ratio (o/e) 0.89, 90% interval 0.75 to 1.07.
Homologues: Orthologues: chimpanzee IGSF23 (97% identical), macaque IGSF23 (88% identical), dog IGSF23 (48% identical), mouse Igsf23 (48% identical), rat Igsf23 (43% identical).
Diseases named in the same sentence as IGSF23 in open-access papers:
IGSF23 is named in the same sentence as 6 diseases in open-access papers, as found by Europe PMC text mining. Sharing a sentence is not in itself a finding about the gene and the disease. The quoted sentences say what the papers report.
osteopetrosis (2 papers, 2019 to 2024). Osteopetrosis, also known as marble bone disease, is a descriptive term that refers to a group of rare, heritable disorders of the skeleton characterized by increased bone density on radiographs. "For instance, loss-of-function mutations in the gene IGSF23 were proven to cause osteopetrosis in humans, which is characterized by increased bone mineral density." (PMID 39092175, 2024). "Lastly, we found that the p.R99X mutation showed a perfect co‐segregation associated with the osteopetrosis phenotype by sequencing of IGSF23 from other five samples." (PMID 31560140, 2019). "In our study, we detected a homozygous mutation (c.295C>T) in the IGSF23 coding region from two osteopetrosis samples by using genome‐wide scan and fine mapping study analysis." (PMID 31560140, 2019). "In this study, we found a novel pathogenic gene mutation (IGSF23) from an autosomal recessive osteopetrosis pedigree, the mutation of IGSF23 lead to osteopetrosis as a result of preventing osteoclastogenesis of PBMCs." (PMID 31560140, 2019). "It has been proved that the inactivation of the gene IGSF23 can cause osteopetrosis in humans." (PMID 39092175, 2024). "We found a homozygous mutation (c.295C>T) in the IGSF23 gene in two osteopetrosis samples." (PMID 31560140, 2019). "We found that genes associated with osteopetrosis have undergone positive selection (CSF1R and LRRK1) or pseudogenized (FAM111A and IGSF23) in the African manatee, potentially contributing to the dense bone formation." (PMID 39092175, 2024).
autosomal recessive osteopetrosis (1 paper, 2019). An autosomal recessive form of osteopetrosis caused by mutation(s) in at least 8 genes related to osteoclast function. "In conclusion, this study identified a novel gene mutation of IGSF23, which caused a rare form of autosomal recessive osteopetrosis." (PMID 31560140, 2019). "This study has revealed for the first time the role of human IGSF23 in osteoclastogenesis and demonstrated the involvement of a nonsense mutation in IGSF23 gene in the development of human autosomal recessive osteopetrosis." (PMID 31560140, 2019).
brain tumors (1 paper, 2022). "SMOC1, a SPARC-related ligand overexpressed in brain tumors, recovered BST2, IGSF23, and SMOC2 as the highest-ranking hits." (PMID 36178190, 2022).
osteoporosis (1 paper, 2019). A condition of reduced bone mass, with decreased cortical thickness and a decrease in the number and size of the trabeculae of cancellous bone (but normal chemical composition), resulting in increased fracture incidence. "IGSF23‐mediated osteoclast differentiation of PBMCs may serve as a potential target in osteoporosis therapy." (PMID 31560140, 2019). "Therefore, IGSF23 may be regarded as a new target for osteoporosis." (PMID 31560140, 2019).
cancer (1 paper, 2020). A tumor composed of atypical neoplastic, often pleomorphic cells that invade other tissues. "In other cancer types, such as KIRP, MESO, and CHOL, PVR expression also seems to be related to a putative intergenic enhancer in an intron of IGSF23." (PMID 33343635, 2020).
IGSF23 also shares sentences with these, for which no sentence is quoted: hair diseases (1 paper).